CD163 (CD163 molecule)
Diseases named in the same sentence as CD163 in open-access papers (continued):
Sharing a sentence is not in itself a finding about the gene and the disease.
tumor (continued). "Staining of serial sections with anti-CD163 antibody revealed that the majority of the tumor-infiltrating human macrophages in HSC-NOG-hIL-6 Tg mice were strongly positive for CD163." (PMID 29456539, 2018). "Macrophages exhibiting predominately the anti-inflammatory CD163/CD68 phenotype are known to be tumor-associated M2 macrophages, supporting the tumor, whereas M1 macrophages (CD68) act against the tumor." (PMID 29861851, 2018). "In summary, densities of CD68+ and CD163+ pixels are greater within and close to the edge of the tumor, consistent with attraction of macrophages by the tumor while CD11b+ and CD11c+ pixels reside at a greater distance from the tumor." (PMID 30619287, 2018). "While the greatest percentage (~70%) of CD68+ and CD163+ pixels was 0–20 microns away from tumor and T cell borders, CD11b+ and CD11c+ pixels were detected up to 240 microns away from tumor/T cell masks." (PMID 30619287, 2018). "PD-L1 also showed a varied expression within tumour cells across samples while higher numbers of CD163 positive macrophage aggregations were identified within tumour." (PMID 30400822, 2018). "The tumor areas were also invaded by tumor associated macrophages (TAM), positive for CD68 and CD163 markers." (PMID 30326856, 2018). "Higher tumor grade correlated with higher frequencies of CD163+ TAMs and worse progression-free survival." (PMID 30042343, 2018). "RMG-I and SAS formed tumor in NOG-hIL-6 Tg mice and flowcytometric analysis demonstrated the induction of CD163+IL-4Rα+TAM-like human myeloid cells as in HSC4-tumor." (PMID 29456539, 2018). "The tumor-infiltrating macrophages in HSC-NOG-hIL-6 Tg mice expressed a high level of CD163, a marker of immunoregulatory myeloid cells, and produced immunosuppressive molecules such as arginase-1 (Arg-1), IL-10, and VEGF." (PMID 29456539, 2018). "As the increase in CD163 was intratumor specific, tumor-derived stimuli were necessary for inducing the differentiation into TAM-like cells." (PMID 29456539, 2018). "Significantly more CD68+ and CD163+ vs. CD11b+ and CD11c+ pixels were in direct contact with tumor cells and T cells." (PMID 30619287, 2018). "Using a full panel of immune cell markers (CD3, CD8, PD1, Foxp3, CD68 and CD163), we asked how similar different tumor types were in terms of immune cell spatial layout." (PMID 30179157, 2018). "At 5 w p.i. the 4T1 + RAW264.7 and 4T1 primary tumors showed similar CD163 stainings, but the CD163-positive cells still minimally invaded the tumor tissue." (PMID 30111338, 2018). "Immunostaining of CD163 in cancer cells and macrophage infiltration (MI) in tumor stroma were evaluated." (PMID 29725763, 2018). "Single IF slides were stained for PD-1, PD-L1, CD8, FoxP3, CD163, and a tumor marker (e.g. Sox10/S100 for melanoma) using primary antibodies at manufacturer’s recommended concentrations and visualized with an Opal kit (PerkinElmer)." (PMID 30400835, 2018). "TAMs, including all CD68+ macrophages, as well as CD68+/CD163+ cells were found at the stroma and perivascular areas or filling ductal-like structures and inter-epithelial cell gaps within the tumor islets." (PMID 30558648, 2018). "We derived immune topographies for CD8 and CD163 from cell counts in the outer invasive margin and the tumor core for N = 287 patients using the median cell densities from the pan-cancer cohort as cutoff values." (PMID 30179157, 2018). "We conducted immunohistochemical analysis to detect human macrophages in HSC4-tumor using anti-CD68 or anti-CD163 antibodies, which are markers of macrophages or immunoregulatory macrophages, respectively." (PMID 29456539, 2018). "TAMs are macrophages (characterized as F4/80+CD11b+Ly6Clow in mouse or CD11b+CD14+CD163+ in human) that accumulate in the tumor microenvironment and promote tumor progression." (PMID 30483271, 2018).
tumor (continued). "By contrast, CD163+ M2 macrophages were observed in the tumor periphery and were significantly decreased in the anti‐PD1‐treated mice compared with controls (P < 0.05)." (PMID 29733528, 2018). "High infiltration of CD68+ or CD163+ TAMs was consistently and significantly related to old age, large tumor size, advanced TNM stage, and adjuvant chemotherapy (all P < 0.050)." (PMID 29573574, 2018). "In all three cases, almost all CD163(+) macrophages were found to be donor-derived not only in the tumor but also in the non-tumor tissue." (PMID 30272010, 2018). "To confirm the relevance of TAMs in favoring the aggressiveness of BC cells, we performed double immunofluorescence for CXCR4 and CD163 on tumor tissues of luminal B BC patients from the validation cohort." (PMID 29849822, 2018). "The invasive front, especially regions where budding cells were identified, showed a strong enrichment in CD68- and CD163-positive macrophages when compared to the tumor core (5,5-fold (p<0.001) and 3,5-fold (p= 0,0052 respectively)." (PMID 29731961, 2018). "Subgroup analysis according to the sample locations suggested that elevated CD163+ TAMs density in both total tumor and tumor stroma correlated with unfavourable RFS (HRs = 2.44, 95% CI = 1.50 ~ 3.39, and = 2.08, 95% CI = 1.13 ~ 3.02, respectively)." (PMID 29861872, 2018). "The macrophage differentiation at the primary tumor in the larynx was strongly CD163 positive supporting an immune permissive environment for tumor growth and metastasis." (PMID 28716144, 2017). "We observed CD3+ T cells, CD20+ B cells and CD68+ monocytes/macrophages as well as Foxp3+ Treg cells and CD163+ TAMs to be present in peri- and intra-tumor areas." (PMID 29190964, 2017). "In comparison, only a subset of macrophages (CD68+) in the primary tumour displayed putative M2 markers (CD163+ or COX-2+)." (PMID 28417956, 2017). "In our previous studies, we demonstrated active angiogenesis and accumulation of tumor promoting M2- (CD163+) macrophages in and around MLL-tumors." (PMID 29073272, 2017). "The data thus far show that the differential distribution of each immunologic cell marker (CD8+ or CD163+) in the combined tumor regions has a potential prognostic value for both DFS and OS as clinical endpoints." (PMID 28428887, 2017). "CD163 was detected around the tumor or connective tissue, while CD204 was detected in/around the tumors." (PMID 28496107, 2017). "CD68+ and/or CD163+ myeloid cells (including macrophages and myeloid dendritic cells) were found in the stromal regions within the center of the tumor, demarcated by the cytokeratin+ tumor cells." (PMID 28344870, 2017). "Our data also confirmed CD163 was associated with VCAM1 (r=0.42) and CLECA7 (r=0.71) which had been used to identify tumor associated macrophages recently." (PMID 29152078, 2017). "IHC staining of PTN, the GSC marker SOX2 and the M2 TAM marker CD163 revealed that tumour regions with high levels of PTN expression and CD163+ M2 TAM infiltration contained abundant GSCs marked by SOX2." (PMID 28569747, 2017). "For instance, in case of CSF1R, the humanised monoclonal antibody RG7155 potently inhibited CSF1R dimerisation and also induced a striking reduction in the CSF1R+CD163+ macrophage population within tumour tissues." (PMID 29065107, 2017). "Although CD163 expression in TNM IV is higher than it in TNM I-III, it seemed that change was mainly caused by tumor invasion status (p=0.048)." (PMID 29152078, 2017). "Infiltration of CD68-positive macrophages and CD163-positive M2 macrophages was found in tumor tissue of AITL." (PMID 29100307, 2017). "In this study, we found that CD163-positive M2 macrophages were primarily located in the tumor stroma, a few also distrbuted in the tumor islet of Kazkah ESCCs." (PMID 28423526, 2017).
tumor (continued). "In this case, the PD-L1 decoration involved only a small CD3 positive area that seemed to be enriched in CD14- and CD163-positive cells, which are known to contribute to the formation of a suppressive milieu and thus favour tumor escape." (PMID 28415643, 2017). "In human malignancies, also including BCa, the presence of CD163+ M2 macrophages in the tumor stroma correlated with poor overall survival, while contrasting data have been reported for colorectal cancer." (PMID 28428887, 2017). "All these findings indicate CD163 in cancer cells promotes tumor progress by participate immunomodulation." (PMID 29152078, 2017). "EpCAM, K19 or CD133 expression also showed a significant correlation with those of tumor stromal CD68 (+)/CD163 (+) TAMs and IL-6 (+) stromal cells." (PMID 28114366, 2017). "We observed in our 3D co-culture model that tumor/fibroblast spheroids induced an M2 polarization of co-cultured monocytes with a CD14+ CD163+ HLA-DRlow CD86low ARG-1+ phenotype which resembles the phenotype of TAMs in PDAC." (PMID 28750018, 2017). "The associations of these factors with the expression of CD163+ M2 TAM and PD-1+ TILs were also investigated to elucidate DLBCL host immunity and tumor microenvironment." (PMID 28036275, 2017). "As study had reported tumor cells play an important role in the formation and transformation of macrophages, so we also examined CD163 in the metastatic lymph node." (PMID 29152078, 2017). "In all cases, the analysis revealed throughout the tumor proliferation a low number of T cells, CD3+, and CD8+ and of tumor‐associated macrophages (TAM), CD163+, and/or CD68+, distributed around the vessels." (PMID 28627792, 2017). "Data reported here also confirm elevated CD163 is correlated with tumor differentiation and invasion depth." (PMID 29152078, 2017). "Regarding TAMs, the expression of CD68 (+) or CD163 (+) tumor stromal TAMs significantly increased with progression of multistep hepatocarcinogenesis (both, P <0.001) from LGDN to pHCC." (PMID 28114366, 2017). "IL-6 (+) tumor stromal cells also showed positive correlations with α-SMA (+) CAFs, CD68 (+) and CD163 (+) tumor stromal TAMs." (PMID 28114366, 2017). "Once embedded in the tumour microenvironment, the monocytes mature into the predominant M2 expressing CD163 (haemoglobin scavenger receptor) macrophages and are activated by Th 2 cytokines interleukin-4 (IL-4) and IL-10." (PMID 28913366, 2017). "The localization of these M2 macrophages was similar to M1 macrophages; CD163+ also surrounded and infiltrated the outer edge of the recurrent tumor." (PMID 28076333, 2017). "The number of VM and CD163+ TAMs increased with aggressive tumor biology defined by advanced WHO grade (P < 0.001)." (PMID 27903982, 2017). "IF staining of CD68 and CD68+CD163+ showed that the majority of macrophages belong to the M2 phenotype, suggesting a potential tumor-favorable environment created by macrophages in CM." (PMID 28903377, 2017). "CD68 (+) or CD163 (+) tumor stromal TAMs were all enriched together with EpCAM, K19 and CD133 expression (P <0.05 for all)." (PMID 28114366, 2017). "Expression of CD163 was detected in tumor stroma and around tumors, while that of CD204 was strongly detected in/around tumors." (PMID 28496107, 2017). "In the 38 CRCs included in our cohort, both CD68-positive cells and CD163-positive cells were almost exclusively located in the tissue surrounding the tumors, especially along invasive tumor front." (PMID 28403223, 2017). "That is, we found that patients with a tumor microenvironment (TME) rich in CD163+Foxp3+ CD80+ experience a higher rate of cancer recurrence compared to patients with TME low in CD163+Foxp3+ CD80+." (PMID 28947958, 2017). "The number of infiltrated CD163-positive M2 macrophages in tumor islets and stroma was significantly higher than in cancer adjacent normal tissues." (PMID 28423526, 2017).
tumor (continued). "In the present study, we demonstrate that the combined evaluation of CD8+ or CD163+ immune cell densities in the tumor center and invasive margin allows better stratification and improves the prognostic value of TNM staging in BCa." (PMID 28428887, 2017). "We found that a heparin-binding glycoprotein pleiotrophin (PTN) was consistently and preferentially secreted by the CD11b+/CD163+ TAMs to promote GSC tumour growth." (PMID 28569747, 2017). "Considering tumor tissues were mixture of cancer cells and tumor stroma, we next examined the protein expression of CD163 in 139 tumor tissues and 10 para-cancer tissues by immunohistochemestry assay." (PMID 29152078, 2017). "In our study, both INOS (M1-polarized macrophage markers) and CD163 (M2-polarized macrophage markers) were correlated with the mitotic index, suggesting the distinct involvement of M1- and M2- macrophages in tumor growth." (PMID 27823976, 2016). "These cells are called tumour associated macrophages (TAMs) and are characterized by the expression of CD204, CD206, CD163." (PMID 27846260, 2016). "The expression of Cd163 and Hmox1 were also significantly increased in monocytes stimulated with G-EVs compared to controls, suggesting that both types of tumor-EVs induced an M2-phenotype." (PMID 27550147, 2016). "Some studies have found that TAMs promote tumor progression in CRC patients; CD68+ macrophages are used as a marker of progression, and CD163+ macrophages are associated with early local recurrence and reduced survival times." (PMID 27683110, 2016). "We show that primary human monocytes, co-transplanted with either luminal A or TNBC cells in highly immunodeficient NSG-mice, differentiated into CD163+ myeloid cells and promoted an increased stroma formation in both tumour types." (PMID 27725631, 2016). "We next investigated why the proportion of CD11b+CD163+ myeloid cells was high in the TN co-transplant tumours." (PMID 27725631, 2016). "We also observed the strongest CD68+ and CD163+ TAM infiltration in the tumor stroma and lamina propria." (PMID 27221038, 2016). "In the tumour samples, immunohistochemical staining of CD163 was performed to visualize the CD163-positive macrophages." (PMID 27464733, 2016). "In this study, we assessed the expression of two TAMs markers CD68 and CD163 in tumor or peritumoral tissue specimens." (PMID 26769084, 2016). "High density of CD163+ TAMs in the tumor microenvironment of adult cHL also predicted poor OS (HR: 2.75; 95 % CI, 1.58–4.78) and poor PFS (HR: 1.66; 95 % CI, 1.22–2.27)." (PMID 27745550, 2016). "The present study showed the density of CD163-positive macrophages both in tumor nest and stroma significantly correlated with the overall survival." (PMID 26769084, 2016). "Our data show that different ratio of CD163-positive M2 TAMs exist in tumour tissue samples of DLBCL patients with various disease stages." (PMID 27464733, 2016). "Our results demonstrated that a high density of either CD68+ or CD163+ TAMs in the tumor microenvironment significantly predicted poor OS and shorter PFS for adult cHL (P = 0.000 and P = 0.000, respectively)." (PMID 27745550, 2016). "TAMs showed a M2-like phenotype characterized by expression of Cd206 (Mrc1), Cd163, Pdl2 (Pdcd1lg2), Chi3i3, Arg1, as well as tumour-promoting molecules involved in invasion and metastasis like MMPs." (PMID 27150562, 2016). "Our results showed that 6 days of treatment with tumour homogenates induced M2 macrophage makers, CD163, IL-10 and MMP9 expression, as well as the expression of legumain in U937 cells." (PMID 27464733, 2016). "It has been reported that both CD68 and CD163 express on circulating monocytes and macrophages and used as TAMs markers in tumor progression." (PMID 26769084, 2016). "The objective of this study was to evaluate the prognostic significance of elevated density of CD68+ and CD163+ TAMs in the tumor microenvironment on overall survival (OS) and PFS in patients with adult cHL." (PMID 27745550, 2016).
tumor (continued). "Nevertheless, the expression of M2a markers (that is, CD163 (Cd163), mannose receptor complex-1 (Mrc1) and arginase-1 (Arg1) was significantly upregulated in sST2 low-expressing tumours." (PMID 27882929, 2016). "In contrast, the density of CD163-positive macrophages in the tumor nest and stroma was higher in 59 % (75 out of 127) and 57 % (73 out of 127) of total samples." (PMID 26769084, 2016). "The macrophages present in tumors are generally considered as tumor-associated macrophages (TAMs), which have a M2 phenotype and express CD68 and CD163." (PMID 26769084, 2016). "There was a trend towards a higher number of positive cells for CD68 than CD163 (pro-tumor macrophages) in tumors both before and after the administration of 177Lu-BR96." (PMID 26374556, 2015). "In fact, expression of CD163 on breast cancer cells as well as rectal cancer cells was associated with early recurrences and a reduced survival time, which is generally in view with the concept that tumor cell × normal cell hybrids may exhibit a more malignant phenotype." (PMID 26703575, 2015). "The expression of tissue-specific markers, such as macrophage-specific antigen CD163, by cancer cells can be a reliable means of detecting the presence and significance of fusion in tumor tissue from clinical patient material." (PMID 26585897, 2015). "The CD68 antigen is expressed by all macrophages, neutrophils, basophils, DC, and myeloid progenitor cells (e.g., myeloid-derived suppressor cell), while CD163 is expressed by M2 (pro-tumor macrophages)." (PMID 26374556, 2015). "At baseline patient R356 had more (CD3 x33, CD4 x10, CD8 x9, CD11c x21, CD68 x15, CD163 x12) immunological cells in the tumor than patient O340." (PMID 25714011, 2015). "Tumor weight correlated to volume densities of CD163+ macrophages in TINT surrounding G (Rs = 0.60, p<0.05), AT-1 (Rs = 0.67, p<0.05) and MatLyLu (Rs = 0.73 p<0.05) tumors." (PMID 26536349, 2015). "Although widely accepted as a specific monocyte/macrophage marker, CD163 can also be expressed by immature MDCs, which include myeloid-derived suppressor cells (MDSCs), known to favor tumor progression." (PMID 26243145, 2015). "Since galectin-1 was practically always expressed by tumor infiltrating immune cells and galectin-3 among non-tumor cells by CD163+ macrophages, the galectin-1/3 double positive cells are expected to be tumor epithelium infiltrating CD163+ macrophages." (PMID 26066796, 2015). "A cytotoxic tumor microenvironment, defined by a CD8+/FOXP3+ ratio >1.5 was associated with higher numbers of CD68+pSTAT1+ (P=0.025) and CD163+pSTAT1+ macrophages (P<0.0005)." (PMID 25978381, 2015). "These macrophages were, however, mainly CD163- as the density of CD163+ macrophages inside the G tumor was low." (PMID 26536349, 2015). "This analysis showed that small AT-1 tumors were more effective than small G tumors in recruiting CD68+ and CD163+ macrophages, and in stimulating vascular growth, to the tumor-bearing organ." (PMID 26536349, 2015). "Tumor-associated macrophages (TAMs) are generally considered M2c-like macrophages, expressing CD206 and CD163." (PMID 25972766, 2015). "Most galectin-1 expressing cells infiltrating in the tumor epithelium were macrophages, predominantly CD163+ type 2 macrophages." (PMID 26066796, 2015). "In this study, we detected a significantly higher frequency of circulating and tumor infiltrating CD14+CD169+CD163+ and CD14+CD163+CD206+ M2-like macrophages in CRC patients." (PMID 26509874, 2015). "CD163 positive cancer cells in tumor sections grew in clonal collection and a cutoff point >25 % of positive cancer cells was significantly correlated to disease free and overall survival." (PMID 26585897, 2015). "CD163 expression in cancer cells was significantly related to advanced tumor stages and poor survival." (PMID 26585897, 2015).